IDO1 (indoleamine 2,3-dioxygenase 1)
Diseases named in the same sentence as IDO1 in open-access papers (continued):
Sharing a sentence is not in itself a finding about the gene and the disease.
colitis (continued). "In addition, DSS-induced colitis increased the expression of the indoleamine 2,3-dioxygenase 1 (IDO-1) gene (t14 = −3.2; p = 0.007), which has been suggested as an important link between microglial activation and behaviour." (PMID 31882991, 2019). "IDO-1 knockout mice exhibit worse colitis, T-cell infiltration and mortality." (PMID 31181125, 2019). "We also observed increased IDO-1 gene expression in the mPFC of mice with colitis." (PMID 31882991, 2019). "Also, disease severity was worsened in mice with trinitrobenzenesulfonic acid induced colitis receiving IDO-1 inhibition." (PMID 31181125, 2019). "Indeed, in the 2,4,6-trinitrobenzene sulfonic acid (TNBS)-induced colitis model, disease severity is exacerbated in IDO1 deficient mice or mice receiving an IDO inhibitor." (PMID 30697218, 2018). "Pharmacological inhibition of IDO1 by L-1MT attenuated the severity of DSS-colitis as well." (PMID 26610689, 2015). "We showed that DSS-treated IDO1-deficient mice did not develop colitis of the same severity as normal control mice by assessing the loss in body weight, intestinal bleeding, diarrhea, shortening of colon length and histological lesions." (PMID 26610689, 2015). "To verify the role of IDO1 in the expansion of CD11+Gr-1+ cells in the DSS-induced colitis model, we examined whether treatment with the IDO1 inhibitor, L-1MT, would reproduce the results from Ido1−/− mice." (PMID 26610689, 2015). "In addition, we further examined the pathophysiological roles played by IDO1 in colitis development in studies using DSS-induced colitis model." (PMID 26610689, 2015). "Based on the array analyses showing that the inflammatory response was the most significant biological process affected by the absence of IDO1 in untreated mice, we next sought to study the effects of IDO1 deficiency on colitis development." (PMID 26610689, 2015). "This large-scale profiling may enhance our understandings of the contributions of IDO1 to colitis development, and provide novel target genes regulated by IDO1." (PMID 26610689, 2015). "Additionally, IDO1 activity, identified through increased xanthurenate, has been shown to negatively correlate with intestinal inflammation itself, and modification upstream of xanthurenate has protected against murine colitis." (PMID 39242821, 2024). "Thus, it is suggested that Clos may confer protection against colitis in humans by ameliorating unbalanced Treg/Th17 responses through enhancement of IDO1 expression." (PMID 38351003, 2024). "Furthermore, the therapeutic effects of CA might be associated with its modulation on tryptophan metabolism, evidenced by CA inhibited the upregulation of IDO-1 in colon tissue of colitis mice and IFN-γ induced RAW264.7 cells." (PMID 36741371, 2022). "Additionally, IDO1 were over-expressed in inflamed and adenoma of the colon, also functioned in promotes colitis-associated tumorigenesis independent of T-cell immune surveillance." (PMID 31214045, 2019). "Furthermore, to explore whether pharmacological inhibition of IDO1 reproduces the results observed following Ido1 gene deletion, we administered Ido1+/+ mice with L-1MT, a specific IDO1 inhibitor, then followed by colitis induction with 2% DSS treatment." (PMID 26610689, 2015). "Moreover, IDO1 has been demonstrated to promote colitis-associated tumorigenesis in mice, independent of its ability to limit T-cell–mediated immune surveillance." (PMID 26359356, 2015). "In 7-week-old non-inflamed Il10−/− mice, increased Ido1 gene expression might also be important in the early response to commensal bacteria preceding colitis due to the deficiency of the Il10 gene." (PMID 20671959, 2010). "The expression levels of IDO1, GRP78 and XBP1 were significantly elevated during the acute colitis phase of UC in the four GEO cohorts." (PMID 40370742, 2025).
colitis (continued). "Consistent with our findings of upregulated Ido1 expression in the Winnie mouse colon, IDO1 is increased in tissues from IBD patients and other animal models of colitis in response to inflammation." (PMID 39015786, 2024). "Altogether, we demonstrated that Trp metabolism in DCs was promoted by Dub, and the resulting Kyn enhancement from strengthened IDO1 expression rebalanced Treg/Th17 responses and ultimately exerted a protective effect on DSS-induced colitis." (PMID 38351003, 2024). "Indoleamine 2,3 dioxygenase-1 (IDO1), a key enzyme in tryptophan metabolism, is strongly up-regulated both in human inflammatory bowel disease (IBD) and animal models of colitis, however its role in the pathogenesis is still controversial." (PMID 36798536, 2023). "Na2SeO3 regulates the IDO1/kynurenine, TLR4, NF- κB, and Bcl2/Bax pathways and attenuates acetic acid-induced colitis in rats." (PMID 39280958, 2022). "In the experimental colitis model, the administration of the TLR-9 agonist improved clinical and histological parameters via the induction of IDO1, and the inhibition of IDO1 activity abrogated the protective effects." (PMID 33413597, 2021). "In agreement with this is the fact that inflammation was reduced in Stat1−/− mice following DSS treatment, and an Ido1−/− mouse (Ido1 is up-regulated in S839I mice) shows a reduced severity to DSS-induced colitis." (PMID 34546338, 2021). "A previous study reported that inhibition of Ido1 and consequent downregulation of TLR and NF-κB signaling pathways attenuates the severity of DSS-induced colitis and modulates the inflammatory response." (PMID 32123204, 2020). "In line with this notion, IDO-1 is one of the most up-regulated genes in human IBD and animal models of colitis." (PMID 31181125, 2019). "Interestingly, high expression of IDO1 has also been observed in experimental murine colitis and in human inflammatory bowel disease, a condition that is associated with a significant increase in the risk of CRC, further suggesting a role for IDO1 in the development and progression of CRC." (PMID 22108515, 2012). "Colitis was induced in mice via dextran sulfate sodium (DSS) treatment and subsequently treated with oral administration of 1-methyl-DL-tryptophan (1-MT), an inhibitor of IDO1 pathway." (PMID 40370742, 2025). "DSS-induced colitis caused elevated KYN levels in the cerebral cortex, which were primarily a result of local synthesis mediated by the IDO-1, rather than transport from the bloodstream." (PMID 38247868, 2024). "While IDO1 upregulation is well established in acute colitis, no clear evidence is available on the modulation of IDO1 levels during the chronic phase of DSS-colitis." (PMID 36798536, 2023). "In summing up, the main mechanism by which Gal-3 regulates immunosuppressive capacity of regulatory DCs in the gut is relied on the TLR-4-dependent activation of IDO-1/KYN pathway and consequent expansion of colon-infiltrated Tregs which suppress Th1 and Th17 cell-driven colon inflammation." (PMID 31336879, 2019). "Therefore, IDO-1 expression is increased in the gastrointestinal (GI) tract of both humans with inflammatory bowel disease (IBD) and animal models of colitis, due to overexpression of pro-inflammatory cytokines and over-activation of toll-like receptors." (PMID 31181125, 2019). "Studies of the DSS-induced colitis model system enabled us to characterize the role of IDO1 in driving inflammatory response, which is not apparent in the non-stimulated state." (PMID 26610689, 2015). "Importantly, this was not due to IDO1 inhibition impacting on severity of colitis, confirming the tumour promoting effects of increased epithelial IDO1 activity following Dock2 deletion." (PMID 39242821, 2024).
autoimmune disease (54 papers, 2012 to 2026). A disorder resulting from loss of function or tissue destruction of an organ or multiple organs, arising from humoral or cellular immune responses of the individual to their own tissue constituents. "Accordingly, serum TRP concentrations were found to be low and linked to poor prognosis in autoimmune disorders involving IDO-1 activation and Th1 type cellular immune response." (PMID 32604956, 2020). "IDO1 is induced and activated by various inflammatory stimuli and there is ample evidence that activation of the IDO1 enzyme causes immunosuppression in several chronic inflammatory conditions, e.g., autoimmune diseases, bacterial and viral infections, and in various tumors." (PMID 37081894, 2023). "The deficiency of IDO-1 enzyme has been reported in a number of autoimmune disorders." (PMID 32604956, 2020). "Targeting this axis, for instance through combined HIF-1α inhibitors and IDO1/AhR pathway agonists, holds promise as a novel metabolic intervention strategy for autoimmune diseases." (PMID 41869303, 2026). "Previous studies have demonstrated that IDO1, a pivotal immune regulator, plays an essential role in macrophage polarization and various diseases, particularly in autoimmune disorders." (PMID 40370742, 2025). "In inflammatory diseases, the expression of IDO1 helps to maintain immune homeostasis and prevents the onset of autoimmune diseases." (PMID 40916319, 2025). "Indoleamine 2, 3-dioxygenase-1 (IDO1) is now considered as a well-established immune regulator in autoimmune diseases, chronic inflammation, and tumor immunity." (PMID 40370742, 2025). "There is substantial evidence that the activation of novel immune checkpoint IDO1 induces immunosuppression in autoimmune diseases, bacterial and viral infections, and many cancers." (PMID 39065567, 2024). "Meanwhile, IDO1 is regarded as a target gene to regulate overactive immune responses in human autoimmune diseases." (PMID 37214338, 2023). "IDO1 is associated with many disorders of immune function, including cancer, HBV infection, allergy, and autoimmune diseases." (PMID 37867998, 2023). "Trp-Kyn metabolism via IDO1 induction has also been reported with clinical relevance in other autoimmune diseases." (PMID 35778590, 2022). "These authors also showed that the TGFβ/IDO1 axis plays important role in mediating durable regulatory functions in B cells, indicating new perspectives for future management of autoimmune diseases." (PMID 34576041, 2021). "Among the known endocrinopathies, T1DM is an autoimmune disorder, in which the significance of IDO1 activation is relatively well described." (PMID 34576041, 2021). "In terms of maintaining immune tolerance, IDO1 plays a pivotal role in the tumor microenvironment and autoimmune diseases." (PMID 34183017, 2021). "Further investigations on arginine metabolism in the aging process, neoplasia, and also autoimmune disorders, and its possible relationship with IDO1 is a new pathway to be explored, with possible therapeutic purposes." (PMID 34389039, 2021). "Current studies showed a multifarious and pivotal role of IDO1 in immunoregulation during infection, pregnancy, autoimmune diseases, and neoplasia of various origins." (PMID 34576041, 2021). "Throughout this review, we will center our attention on the role of IDO1 in immunosuppression and experimental approaches that modulate IDO1 expression for the prevention and treatment of chronic inflammatory and autoimmune diseases." (PMID 26378585, 2015). "The activity of IDO1 increases in various inflammatory diseases, including tumors, autoimmune diseases, and different kinds of inflammation." (PMID 24533148, 2014). "Furthermore, in autoimmune disorders such as rheumatoid arthritis, the aberrant activation of M1 macrophages and the dysregulated expression of IDO1 contribute to chronic inflammation and tissue damage." (PMID 40370742, 2025).
autoimmune disease (continued). "There is a paucity of evidence showing mutations of IDO1 and AHR genes that are linked to a direct cause-and-effect relationship with autoimmune diseases; however, functional defects of IDO1 caused by various factors are observed in autoimmune diseases." (PMID 37394584, 2023). "Moreover, drugs that influence IDO1 have been shown to have a high potential in treating autoimmune diseases." (PMID 35327409, 2022). "Subsequently, extensive studies have demonstrated the immunological regulation role for IDO1 in physiological and pathological states including pregnancy, obesity, transplantation, infectious diseases, autoimmune diseases, neurological diseases, and neoplastic diseases." (PMID 35003126, 2021). "Interestingly, IDO1 and TDO2, two key genes in tryptophan metabolism, recently were suggested to associate with autoimmune disease and tumor progression, prompt the immune response involved in the pathogenesis of RPE/choroid in AMD." (PMID 32904543, 2020). "Data from the literature indicate that in many pathologic states (cerebral ischemia, Alzheimer’s disease, Parkinson’s disease, Huntington’s disease, multiple sclerosis, amyotrophic lateral sclerosis, autoimmune diseases, and tumor), IDO1/2 activity increases in microglial/macrophage cells." (PMID 30050435, 2018). "The enzyme IDO1 catalyzes the degradation of tryptophan to kynurenine, with well-established immunosuppressive effects in mammalian pregnancy, tumor resistance, chronic infection and autoimmune diseases." (PMID 22844400, 2012). "Understanding the mechanism of chimeric vaccine modulation of IDO1 induction and suppression of in human dendritic cell activation will facilitate development of chimeric vaccine strategies for effective and safe therapy for type 1 diabetes and a wide range of tissue specific autoimmune diseases." (PMID 26881431, 2016). "Interestingly, the symptoms of GD, similarly to other autoimmune diseases, significantly ameliorate during pregnancy and reappear at postpartum, due to the fact that placenta syncytiotrophoblasts can synthesize the immunologically active molecules, including IDO1, which suppress immune responses." (PMID 34576041, 2021). "Indoleamine-2,3-dioxygenase 1 (IDO1), Arginase 1 (ARG1), the main catabolizing enzymes in tryptophan and arginine metabolism are studied in autoimmune diseases." (PMID 32341806, 2020). "We summarized the existing metabolic targets used in DMARDS and highlighted several future potential targets to treat autoimmune diseases including mTOR, GCN2, IDO1, ARG 1, kynurenine, cysteine, S1P receptor and fatty acid enzymes." (PMID 32341806, 2020). "Here, we discuss the possible protective vs. pathogenetic roles of the interplay between IDO1 and ARG1 in reprogramming immune cell functions in neoplasia and autoimmune diseases." (PMID 31354721, 2019). "The aim with this study was to elucidate how IDO1 and PD-L2 are expressed in benign lymphadenopathies in patients with autoimmune diseases (AD) compared to patients without AD." (PMID 36830609, 2023). "Consequently, it is critical to elucidate the detailed mechanisms and distinguish the individual contribution of IDO1 vs. IDO2 in cancer and/or autoimmune diseases." (PMID 37408267, 2023). "Although an impaired IDO1-mediated TRP metabolism has been observed in distinct autoimmune diseases, so far there are not much data in the available literature, concerning the role of IDO1 and the activation of KP in autoimmunological endocrinopathies." (PMID 34576041, 2021). "IDO has been suggested to play a key role in a variety of autoimmune diseases, including MRL/lpr mouse models of lupus-like diseases, and in another study, IDO1 protein and IDO total enzyme activity were significantly increased in lupus-prone B6.Nba2 mice compared to B6 controls." (PMID 35197962, 2021).
autoimmune disease (continued). "In experimental models of rheumatoid arthritis (RA), an inflammatory/autoimmune disease of the capsule surrounding joints, lack of IDO1 expression reduces the time to develop a more severe disease." (PMID 31354721, 2019). "In autoimmune diseases such as rheumatoid arthritis (RA), systemic lupus erythematosus (SLE), multiple sclerosis (MS), and membranous nephropathy (MN), dysregulation of this axis is characterized by excessive HIF-1α signaling and relative insufficiency of the IDO1/AhR pathway." (PMID 41869303, 2026). "These approaches have generally increased the production of immunosuppressive molecules, including IDO1, PGE2, and TGF-β1, which inhibited the functions of T cells, dendritic cells, and M1 macrophages and showed therapeutic effects in animal models of diverse autoimmune diseases." (PMID 39684336, 2024). "However, compared to IDO1, in vivo studies demonstrated a contrasting role for IDO2, with experiments in preclinical models of autoimmune arthritis establishing a proinflammatory role for IDO2 in mediating B and T cell activation driving autoimmune disease." (PMID 32973768, 2020). "Indeed, several negative feedback mechanisms such as secretion of IL10, IDO1 and TGFβ are induced during immune activation to maintain homeostasis and prevent excessive immune responses that could lead to tissue damage or autoimmune diseases." (PMID 40756372, 2025).